GFAP (glial fibrillary acidic protein)
Diseases named in the same sentence as GFAP in open-access papers (continued):
Sharing a sentence is not in itself a finding about the gene and the disease.
dementia (continued). "The results of this study suggest that in cognitive impairment in PD, elevated plasma GFAP and NfL levels precede the appearance of abnormalities in Aβ 42/40 and p-tau181 levels, which occur only after marked progression of dementia." (PMID 37480401, 2023). "From preclinical to symptomatic stages of AD, plasma GFAP started to rise sharply as soon as CSF Aβ became abnormal and continued to increase until reaching its highest level during the AD dementia phase." (PMID 36750875, 2023). "In males, astrogliosis (GFAP % area covered) was unaffected by either diet or dementia in any of the regions assessed." (PMID 35568928, 2022). "Serum GFAP levels have also been shown to predict future cognitive decline and progression to dementia in CU individuals (Table EV3)." (PMID 34859598, 2022). "A study with a long follow-up compared baseline blood-based biomarkers (Aβ misfolding, NfL, p-tau181 and GFAP) in 308 participants: 68 of whom developed dementia within 17 years." (PMID 36351888, 2022). "Although total cell numbers remained stable, there was a phenotypic change in astrocytes in the temporal pole in the setting of dementia with a significantly higher number of GFAP + activated astrocytes compared to both controls and resilient brains." (PMID 35534858, 2022). "In uncorrected models, t-tau, MTA, HV, NfL, and GFAP all predicted clinical progression to MCI or dementia (model 1)." (PMID 35110378, 2022). "In males, GFAP gene expression in hippocampal homogenate was increased overall by dementia (p < 0.05)." (PMID 35568928, 2022). "Previous studies reported that the serum GFAP has potentials to predict future conversion to dementia in cognitively normal individuals, not only to AD, but also to other dementias including FTD." (PMID 34893073, 2021). "Similar to TRIAD, patients with FTD and dementia with Lewy bodies had plasma and CSF GFAP levels comparable to CU– individuals (eFigure 3C and 3D in Supplement 1)." (PMID 34661615, 2021). "Both studies also show that patients later evolving to dementia have higher baseline GFAP concentrations." (PMID 33773595, 2021). "In this study, our aim was to evaluate plasma GFAP as a potential plasma biomarker of AD in MCI patients, and assess its association with AD-related Aβ pathology and conversion to AD dementia." (PMID 33773595, 2021). "In the present work, we showed that both plasma Abeta(1-42/1-40) and plasma GFAP are independently associated with amyloid pathology as measured by PET in a cohort of individuals with SCD, MCI, and AD-dementia." (PMID 32988409, 2020). "The novel CSF markers NFL and GFAP show potential as markers for cognitive decline among individuals with core AD pathology at the symptomatic pre- and early stages of dementia." (PMID 32753068, 2020). "Our findings suggest that levels of CSF markers NFL and GFAP relate to different cognitive profiles at the symptomatic pre- and early dementia stages." (PMID 32753068, 2020). "We compared different CSF biomarkers reflecting neurodegeneration (NFL) and inflammation (YKL-40, S100B and GFAP) in relation to core CSF AD markers and cognitive functions in a cohort of subjects at the pre- and early symptomatic dementia stages." (PMID 32753068, 2020). "GFAP biosynthesis is induced in activated glial cells, and its presence in cerebrospinal fluid is a biomarker of AD or related dementias." (PMID 31920540, 2019). "In AD, the extent of astrogliosis, as shown by GFAP levels in both cortex and cerebrospinal fluid (CSF) is correlated to the degree of dementia." (PMID 22577599, 2012). "Levels of GFAP in CSF of AD cases are elevated and correlate to the severity of dementia, which is in contrast with our findings in PD cases." (PMID 22577599, 2012).
dementia (continued). "More recent studies align with these findings, showing that WMH, a marker of CAA, and glial fibrillary acidic protein (GFAP), a marker of astrocytosis and neuroinflammation, are independently associated with progression from mild cognitive impairment (MCI) to dementia." (PMID 40604347, 2025). "Compared to the association with GFAP, time to dementia showed a stronger negative correlation with NEFL (Beta = −0.033, P=1.4e-14)." (PMID 40061357, 2025). "Additionally, elevated plasma levels of proteins associated with the glial response, such as glial fibrillary acidic protein (GFAP), observed in prodromal stages of dementia and AD, underscore the importance of neuroinflammation as a precursor event in DS." (PMID 40740212, 2025). "Quantification of astroglial reactivity marker Glial fibrillary acidic protein (GFAP) using Enzyme-linked immunosorbent assay in postmortem brain tissue of dementia patients showed a negative correlation with cognitive function." (PMID 40177583, 2025). "Furthermore, compared to patients with tau (–) dementia, those with tau (+) dementia had higher levels of p-tau217 (p = 0.043), and GFAP (p = 0.004)." (PMID 40181481, 2025). "Elevated baseline levels of p-tau181, p-tau217, NfL, and GFAP were associated with a higher hazard of developing all-cause dementia during the follow-up period, displaying a non-linear relationship." (PMID 40140622, 2025). "GFAP and S100 are important biomarkers of astrocytes, often showing elevated expression in many neurodegenerative diseases such as PD, AD, multiple system atrophy, and dementia with Lewy bodies." (PMID 40988734, 2025). "In addition to replicating previous findings that GFAP and NEFL are associated with greater risk for incident dementia, we found that APOE4 is associated with higher levels of GFAP and NEFL." (PMID 40061357, 2025). "Future studies incorporating younger individuals are necessary to determine whether these genetic effects on NEFL and GFAP are present from a young age or emerge as an early feature of prodromal dementia." (PMID 40061357, 2025). "Future studies, particularly those incorporating AD-specific biomarkers and accessible blood biomarkers such as glial fibrillary acidic protein to evaluate the severity of neuroinflammation, would be invaluable for determining the effects of eradication therapy on incident dementia." (PMID 39129052, 2025). "Overall, individuals who developed dementia had lower baseline amyloid β42/40 and higher baseline levels of p-tau181, p-tau217, t-tau, NfL, and GFAP than those who did not develop all-cause and AD dementia." (PMID 40140622, 2025). "Appropriate quantification of GFAP levels in different forms of dementia would be worthwhile." (PMID 41002922, 2025). "Additionally, by analyzing plasma proteomic data, levels of glial fibrillary acidic protein (GFAP) were identified as predictors of dementia up to 15 years before onset, showcasing the profound potential of proteomics in pre-emptive disease risk assessment." (PMID 40842868, 2025). "AD co-pathology in other dementias, such as elevated p-tau and GFAP levels in FTD and DLB, may account for these differences." (PMID 40115175, 2025). "Both GFAP and NEFL in midlife predict future dementia risk, indicating interventions may need to start in midlife." (PMID 40061357, 2025). "Unlike the parsimonious model with any-cause dementia as outcome, the AD-specific biomarker pTau181 was selected in addition to GFAP for the AD dementia parsimonious model, which had superior discrimination compared to the demographic only model (eTable 2)." (PMID 41339948, 2025). "In AD, for example, the addition of GFAP and ApoE genotype to plasma p-tau217 significantly improved the prediction of amyloid positivity, while cognitive metrics further enhanced the prediction of progression to dementia." (PMID 40640892, 2025).
dementia (continued). "In agreement with previous findings, core AD biomarkers were associated with disease severity both in clinical diagnostic and clinico-pathological groups, with stepwise increases of p-tau 217, NfL and GFAP from cognitively unimpaired (CU) to dementia (p < 0.05)." (PMID 41282064, 2025). "In contrast to GFAP, the magnitude of plasma and CSF NfL elevations is not higher in AD than in other dementia types and does not associate with amyloid or p-τ pathology at autopsy." (PMID 40087672, 2025). "Interestingly, elevated concentrations of GFAP within the CSF have been reported in patients with AD and other forms of dementia compared to healthy individuals." (PMID 39080712, 2024). "GFAP may be a valuable biomarker for predicting cognitive decline and dementia conversion in PD patients." (PMID 39596444, 2024). "GFAP is a strong prognostic blood-based biomarker of the incidence of dementia in older adults." (PMID 39297507, 2024). "The GFAP marker showed promise in predicting the severity of dementia progression later in life, while the YKL-40 marker could indicate the onset of Aβ-related pathological processes." (PMID 38920976, 2024). "However, the predictive value of GFAP and NfL for dementia requires more evidence from population-based cohorts." (PMID 38735950, 2024). "First, the current results reinforce previous findings that GFAP and NEFL may have the potential not only to predict the overall risk of developing dementia but also to serve as specific biomarkers to assess AD risk." (PMID 39252463, 2024). "Moreover, few studies have investigated the combination of GFAP, NfL, and pTau 181 in the preclinical stage of dementia." (PMID 38654932, 2024). "Peripheral GFAP and NfL increased up to 15 years before dementia diagnosis was made." (PMID 38735950, 2024). "Both GFAP and NfL significantly interacted synergistically with AD PRS to increase all-dementia risk (> 10% of TE is pure interaction), while GFAP was also an important consistent mediator in the AD PRS-dementia relationship." (PMID 39586964, 2024). "Therefore, GFAP has emerged as a promising biomarker in dementia related to AD, but further evidence is required in relation to its utility as a biomarker of other kinds of dementia diseases." (PMID 38216970, 2024). "Finally, the diagnosis of dementia is registry-based, limiting the exploration of the relationship between GFAP, NfL, and other compulsory factors for dementia diagnosis." (PMID 38735950, 2024). "Higher plasma GFAP levels showed an almost linear positive association with the risk of all‐cause dementia around a plasma GFAP level of 300 pg/mL and then plateaued (P for nonlinearity = 0.03)." (PMID 38606661, 2024). "The association between plasma GFAP and incident dementia was not explained by the SVD burden score (model 3)." (PMID 37530894, 2024). "Notably, plasma GFAP was the earliest increased and the largest fold-changed indicator in the dementia stage, as well as the more large changes in autosomal dominant AD than in sporadic AD." (PMID 38216970, 2024). "These proteins were chosen because blood GFAP is an FDA authorized marker in individuals with suspected TBI and both the proteins have distinguished roles in synaptic plasticity and neurogenesis, with reported associations in Parkinson’s and dementia." (PMID 38735925, 2024). "GFAP levels have recently been reported to be predictive of conversion of MCI to AD-dementia in several studies with steeper trends of conversion for cognitively abnormal groups and were able to discriminate between MCI individuals who progressed to dementia and non-progressors." (PMID 38720902, 2024). "The CNS damage markers neurofilament light chain protein (NfL), total Tau protein (t-Tau) and glial fibrillary acidic protein (GFAP) are constituent parts of neurons and glial cells that have primarily been used in neurological diagnostics for dementia and demyelinating diseases." (PMID 39048548, 2024).
dementia (continued). "However, GFAP levels are higher in AD patients compared to other conditions and can be used alongside plasma p-tau181 to differentiate between different types of dementia." (PMID 38352136, 2024). "Only two prospective studies have assessed the association between serum GFAP levels and risk of dementia, and no prospective studies, to our knowledge, have investigated this association using plasma GFAP." (PMID 38606661, 2024). "GFAP and P-tau181 could also be a potential biomarker for dementia in Southeast Asians and more research is needed." (PMID 39044522, 2024). "Plasma glial fibrillary acidic protein (GFAP), which is a marker of neuroinflammation and reflects astrocytosis, is also associated with amyloid deposition in healthy controls, and SCI, MCI, and AD dementia patients." (PMID 38623387, 2024). "The study suggested that the markers YKL-40 (CHI3L1), a glycoprotein derived from astrocytes, and GFAP (a marker related to astrogliosis) detected in plasma, could serve as effective indicators, particularly in pre-dementia patients." (PMID 38920976, 2024). "In Long’s study recruited 818 GFAP–astrocytopathy individuals, 15.8% had dementia symptoms." (PMID 38216970, 2024). "To determine the potential of baseline CSF GFAP levels to serve as a predictor of cognitive transition (from NC to MCI or dementia, or from MCI to dementia) in patients with newly diagnosed PD over an 8-year follow-up period, we performed Kaplan–Meier survival curves and Cox regression analysis." (PMID 37475029, 2023). "We suggest that plasma GFAP might have prognostic value for predicting MCI-to-dementia conversion in PD." (PMID 36759508, 2023). "Thus, there is an urgent need for further studies to investigate the potential relationship between SSRI use, serum GFAP and other potential links to incident dementia." (PMID 40980097, 2023). "For dementia, NEFL, BCAN, GFAP, and GDF15 were the main proteins influencing disease risk." (PMID 38016990, 2023). "Although the results need to be confirmed with a larger sample size, it is worth noting that plasma GFAP measurement may be useful as a marker for predicting the transition from MCI to dementia in PD." (PMID 36759508, 2023). "APOE4 status was associated to P-tau181 and GFAP, but not NfL levels in blood at baseline (0–17 years before dementia diagnosis)." (PMID 37516890, 2023). "However, they cannot be compared with our findings because the ESTHER study is a prospective cohort, and GFAP measurements were performed in baseline blood taken at recruitment, years before diagnoses of dementia and depression were made." (PMID 37951931, 2023). "The aim of this study was to explore the association of kidney function with risk of incident AD or dementia diagnosis within 17 years and with the dementia-related blood biomarkers NfL, p-tau181, and glial fibrillary acidic protein (GFAP) in a prospective community-based cohort study." (PMID 36692879, 2023). "In addition, while our study included up to 15 years of follow‐up data on incident dementia status, circulating GFAP levels were only evaluated cross‐sectionally." (PMID 36056631, 2022). "Additionally, our data support the usefulness of plasma p-tau181 and GFAP in screening for AD co-pathology, even in cases with alternative primary dementias." (PMID 36221099, 2022). "However, prior studies have reported elevations in blood‐derived GFAP levels across multiple dementia subtypes including vascular dementia, frontotemporal dementia, Parkinson's disease, and Creutzfeldt‐Jakob disease." (PMID 36056631, 2022). "The pattern of results remained unchanged when dementia surveillance was delayed for at least 2 years following the blood draw for GFAP, further suggesting that elevations in the biomarker may precede dementia onset." (PMID 36056631, 2022).
dementia (continued). "For example, some studies postulated that an increase in the astrocytic marker GFAP is protective against AD-related dementia, which would be in agreement with the increase in Gfap mRNA expression observed here in cognitive resilient mice, while others reported the contrary." (PMID 34502030, 2021). "Moreover, the levels of GFAP IR has a clear tendency to increase in all dementias cases, it was significant higher in FAD." (PMID 34025357, 2021). "This also suggests that plasma GFAP could be very early marker in the pre-dementia phase, like that of our patients at baseline." (PMID 33773595, 2021). "In general, little is known about the role of GFAP in AD and other dementias." (PMID 26029153, 2015). "Furthermore, additional proteins which were consistently altered in both the FLNC-, GRN- and VCP-unique datasets, e.g. GFAP, NPTN, DBI, PRDX6, MARCKS and BSN, are closely associated with cognitive function, dementia and pathological aging." (PMID 26555887, 2015). "Morphologically, the plaque pathology in the AD cohort was distinct from the control and dementia sections; AD cases had a significant increase in dense-core (one-way ANOVA P < 0.01) and GFAP-associated, that is, degraded plaque subtypes (one-way ANOVA P < 0.001)." (PMID 25215243, 2014). "Conversely, the association of p-tau and GFAP with dementia was similar among individuals with and without impaired kidney function, suggesting that CKD might not alter the association between AD-like neuropathology and dementia development." (PMID 41337685, 2026). "In addition, GFAP can be used specifically to predict the onset of dementia, and repeated measurements of GFAP in the preclinical phase of dementia may be more valuable as an indicator of future treatment efficacy in a health clinic." (PMID 40806404, 2025). "Moreover, a recent community-based study in older adults found that elevated baseline p-tau181 and GFAP—but not p-tau217—were more strongly associated with future dementia onset in individuals aged 78 years and above." (PMID 41180536, 2025). "Despite the numerous limitations and unresolved issues surrounding blood GFAP level elevations, these levels remain broadly accepted as biomarkers reflecting neurodegenerative disease stages, not only specific to AD but also early amyloidosis, dementia or faster cognitive decline." (PMID 40346659, 2025). "However, plasma GFAP levels are significantly higher in AD and dementia with Lewy bodies compared to other dementias, suggesting that GFAP may be particularly useful in differentiating AD from frontotemporal dementia and Parkinson’s disease dementia." (PMID 40690136, 2025). "Our results clearly indicated that not only can blood biomarkers be an effective indicator of cognitive decline in patients with dementia, but the existence of vascular lesions that may affect AD pathology could influence the results of measuring plasma concentration levels of NfL and GFAP." (PMID 40076944, 2025). "Interestingly, in the MCI subset, the model with plasma GFAP had better long-term accuracy when directly compared to pTau217 and all other biomarkers (lowest 5-year Brier score), highlighting its potential value for longer term prediction of dementia." (PMID 41339948, 2025). "In addition, NfL and GFAP showed robust correlations in the whole sample (R = 0.22, (CI: 0.16–0.28), p < 0.0001) but also specifically in the CU (R = 0.23, (CI: 0.16–0.30), p < 0.0001) and dementia (R = 0.10, (CI: −0.25–0.43), p = 0.5) groups." (PMID 41282064, 2025). "We found that utilizing plasma pTau217 results in a best performing prognostic model, but in the absence of this biomarker, GFAP and pTau181 could be used to estimate individualized risk to develop dementia in MCI patients." (PMID 41339948, 2025). "However, higher levels of GFAP were observed in dementia cases." (PMID 38352136, 2024).